NGEF (neuronal guanine nucleotide exchange factor)
Description:
Acts as a guanine nucleotide exchange factor (GEF) which differentially activates the GTPases RHOA, RAC1 and CDC42. Plays a role in axon guidance regulating ephrin-induced growth cone collapse and dendritic spine morphogenesis. Upon activation by ephrin through EPHA4, the GEF activity switches toward RHOA resulting in its activation. Activated RHOA promotes cone retraction at the expense of RAC1- and CDC42-stimulated growth cone extension (By similarity).
Synonyms: ARHGEF27; EPHEXIN
Tractability: Antibody: the Human Protein Atlas places it where antibodies can reach. PROTAC: ubiquitination databases record sites on it; its protein half-life has been measured.
Gene: Protein-coding gene on chromosome 2 (232,878,686 to 233,013,263, reverse strand). Ensembl gene ENSG00000066248.
Subcellular location: Cytoplasm; Membrane; Cell projection, growth cone
Subcellular location (Human Protein Atlas): Cytosol; Plasma membrane
Pathways (Reactome):
Signal Transduction: CDC42 GTPase cycle; G alpha (12/13) signalling events; NRAGE signals death through JNK; RAC1 GTPase cycle; RHOA GTPase cycle
Developmental Biology: EPHA-mediated growth cone collapse
Gene Ontology:
Molecular function: guanyl-nucleotide exchange factor activity; protein binding; ephrin receptor binding
Biological process: ephrin receptor signaling pathway; negative regulation of dendritic spine morphogenesis; regulation of actin cytoskeleton organization; regulation of GTPase activity; regulation of small GTPase mediated signal transduction; regulation of synapse pruning
Cellular component: cytosol; cytoplasm; glutamatergic synapse; growth cone; membrane
Genetic constraint (gnomAD): Loss-of-function variants: 28 observed, 76.7 expected, observed/expected ratio (o/e) 0.37, 90% interval 0.27 to 0.5. The upper end of that interval is the gene's LOEUF score, 0.5, which puts it in group 2 of 6, group 1 being the genes least tolerant of losing a copy. Missense variants: 677 observed, 924.53 expected, observed/expected ratio (o/e) 0.73, 90% interval 0.69 to 0.78. Synonymous variants: 366 observed, 371.61 expected, observed/expected ratio (o/e) 0.98, 90% interval 0.9 to 1.07.
Homologues: Orthologues: chimpanzee NGEF (99% identical), macaque NGEF (97% identical), pig NGEF (87% identical), guinea pig NGEF (86% identical), rat Ngef (86% identical), mouse Ngef (79% identical), dog NGEF (75% identical), tropical clawed frog ngef (59% identical), zebrafish ngef (46% identical), Caenorhabditis elegans ephx-1 (30% identical). Paralogues in human: ARHGEF5 (35% identical), ARHGEF19 (32% identical), ARHGEF15 (28% identical), ARHGEF16 (27% identical), ARHGEF26 (27% identical), ARHGEF35 (10% identical).
Diseases named in the same sentence as NGEF in open-access papers:
NGEF is named in the same sentence as 26 diseases in open-access papers, as found by Europe PMC text mining. Sharing a sentence is not in itself a finding about the gene and the disease. The quoted sentences say what the papers report.
colorectal cancer (4 papers, 2021 to 2025). A primary or metastatic malignant neoplasm that affects the colon or rectum. "Previous studies have demonstrated that NGEF expression is upregulated in malignant thyroid nodules, colorectal cancer and papillary thyroid cancer." (PMID 38764064, 2024).
Abdominal obesity (2 papers, 2020 to 2022). Excessive fat around the stomach and abdomen. "For example, one variant has been found in the NGEF gene, which has been associated with abdominal obesity, while another has been found in FBXL7, which has been associated with metabolic syndrome and with an altered pharmacological response to corticosteroids." (PMID 32872468, 2020). "Neuronal guanine nucleotide exchange factor (NGEF), with its known role linked to abdominal obesity, and F-box/LRR-repeat protein 7 (FBXL7), linked to metabolic syndrome and a modified response to corticosteroids, were among the genes found to be altered." (PMID 36551837, 2022).
breast carcinoma (1 paper, 2024). "We observed that the TRs of certain genes, such as SNX5 and NGEF, strongly correlated with the estrogen receptor (ER) phenotype in breast cancer." (PMID 39349823, 2024).
Cognitive impairment (1 paper, 2020). Abnormal cognition is characterized by deficits in thinking, reasoning, or remembering. "NSE, BDNF, and NGEF are well-established biomarkers of cognitive impairment in PD patients, indicating that they may play a pathogenic role." (PMID 33329296, 2020).
Huntington disease (1 paper, 2023). Huntington disease (HD) is a rare neurodegenerative disorder of the central nervous system characterized by unwanted choreatic movements, behavioral and psychiatric disturbances and dementia. "The NGEF appears as Ephexin in the “Huntington-dependent transcriptional deregulation in Huntington’s disease” pathway." (PMID 36816031, 2023).
lung adenocarcinoma (1 paper, 2024). A carcinoma that arises from the lung and is characterized by the presence of malignant glandular epithelial cells. "Neuronal guanine nucleotide exchange factor (NGEF) plays a key role in several cancers; however, its role in lung adenocarcinoma (LUAD) remains unclear." (PMID 38764064, 2024).
melanoma (1 paper, 2025). A malignant, usually aggressive tumor composed of atypical, neoplastic melanocytes. "We further identified several melanoma-decreased genes uniquely up-regulated by ZDL, including growth factor receptor bound protein 7 (GRB7), neuronal guanine nucleotide exchange factor (NGEF), fatty acid amide hydrolase 2 (FAAH2), and ephrin A3 (EFNA3)." (PMID 40141086, 2025).
Obesity (1 paper, 2015). Accumulation of substantial excess body fat. "Associations of NGEF gene variants with obesity-related index: multivariate linear regression analysis." (PMID 26340433, 2015).
papillary thyroid cancer (1 paper, 2024). "Kaplan-Meier survival curves showed that increased NGEF expression was associated with a shorter OS, which was consistent with the previous results in papillary thyroid cancer." (PMID 38764064, 2024).
pterygium (1 paper, 2024). A wedge-shaped fibrovascular lesion arising from the bulbar conjunctiva and extending to the cornea. "The identification of pivotal feature gene KRT10 and NGEF provide valuable insights into the molecular mechanisms underlying pterygium progression." (PMID 39722894, 2024). "We conducted a rigorous screening process and identified KRT10 and NGEF as crucial genes implicated in the pathogenesis of pterygium." (PMID 39722894, 2024). "Notably, KRT10 and NGEF were consistently identified as hub genes associated with pterygium across all two machine learning methods and WGCNA." (PMID 39722894, 2024). "Using WGCNA, RF, and SVM, we identified KRT10 and NGEF as pivotal feature genes influencing pterygium progression." (PMID 39722894, 2024). "In our analysis of RNA-Seq data derived from 68 samples, we observed a statistically significant elevation in the expression levels of KRT10 and NGEF genes in the pterygium group compared to the bulbar conjunctiva group, with a P-value <0.05." (PMID 39722894, 2024). "The SVM algorithm was also employed to rigorously select hub genes associated with pterygium, revealing five significant genes: KRT10, KRT6B, BTG2, ASPG and NGEF." (PMID 39722894, 2024). "qPCR analysis confirmed the elevated expression of KRT10 and NGEF in pterygium tissues." (PMID 39722894, 2024). "The discovery of pivotal genes, namely, KRT10 and NGEF, coupled with insights into immune cell infiltration patterns and pertinent signaling pathways, establishes a foundation for future research endeavors aimed at deciphering the pathophysiology of pterygium." (PMID 39722894, 2024).
thyroid nodule (1 paper, 2016). A small circumscribed mass in the THYROID GLAND that can be of neoplastic growth or non-neoplastic abnormality. "In the present study, we developed a panel that presents excellent performance in discriminating benign from malignant thyroid nodules by combining only four genes (FN1, GABRB2, NGEF and HMGA2)." (PMID 27793213, 2016).
cancer (7 papers, 2021 to 2025). A tumor composed of atypical neoplastic, often pleomorphic cells that invade other tissues. "For vinorelbine, EPHA2 codes for EPH receptor A2, a tyrosine kinase involved in cancer-related signaling, while NGEF codes for a guanine nucleotide exchange factor associated with signaling from EPH receptor A2, RhoA, Rac1 and CDC42 as well as cellular transformation and tumorigenesis." (PMID 36139690, 2022). "Thus, NGEF may act as an oncogene and may be associated with cancer prognosis." (PMID 38764064, 2024). "However, several reports have demonstrated the involvement of NGEF in cancer." (PMID 38764064, 2024). "Several DEGs identified were known to be involved in several cancers, these include the microRNA MIR-186 and the PPP1R1C genes, both of which were up-regulated in our study, and NGEF, C9orf163, INKA2-AS1 and SULT2B1 which were found to be downregulated." (PMID 36197921, 2022). "Moreover, NGEF expression levels were risen in LUAD compared with controls in GSE31210 (P < 0.001), and its AUC value for the diagnosis of cancer was 0.820 (0.736–0.904)." (PMID 38764064, 2024).
tumor (6 papers, 2020 to 2025). "The R was used to evaluate the associations of NGEF expression with tumor stage, immune infiltration, immune checkpoint inhibitors (ICIs), TMB, and sensitivity to chemotherapy." (PMID 38764064, 2024). "High NGEF expression was an independent prognostic factor for LUAD and was associated with advanced tumor stage, large tumor size, more lymph node metastasis, and worse overall survival (OS)." (PMID 38764064, 2024). "Our results indicate that the high NGEF expression has an advanced tumor stage and worse OS and that NGEF is an independent prognostic factor for LUAD." (PMID 38764064, 2024). "NGEF expression is upregulated in LUAD and is significantly associated with tumor stages, OS probability, immune infiltration, immunotherapy response, and chemotherapy response." (PMID 38764064, 2024). "In LUAD, NGEF mRNA and protein expression levels were upregulated and correlated with advanced tumor stage and worse OS." (PMID 38764064, 2024). "Additionally, the mechanism by which NGEF is involved in tumor migration, invasion, and metastasis needs to be confirmed in vivo and in vitro." (PMID 38764064, 2024). "NGEF expression levels were positively correlated with UICC stage (P = 0.042), tumor size (> 3 cm, P = 0.020), and lymph node metastasis (number ≥ 1, P < 0.001)." (PMID 38764064, 2024). "KALRN, MCF2/Dbl, NGEF/EPHEXIN, ARHGEF7/βPix/COOL-1, CDC42EP2, DOCK9, NET1, TIAM2, ABR, PLEKHG5, RhoBTB2 and PREX1 were identified as being increased at the tumour rim." (PMID 33256106, 2020).
NGEF also shares sentences with these, for which no sentence is quoted: lung carcinoma (4 papers); metastatic tumors (4); depression (3); colon cancer (2); metabolic syndrome (2); Cerebral ischemia (1); glioblastoma (1); lymph node metastasis (1); metastatic cancer (1); mood disorder (1); renal cell carcinoma (1); Stroke (1); viral infection (1).